ENSG00000299088 (novel transcript)
Gene: Long non-coding RNA gene on chromosome 1 (40,131,876 to 40,135,936, forward strand). Ensembl gene ENSG00000299088.
Gene Ontology:
Biological process: translational frameshifting